PIN1 (peptidylprolyl cis/trans isomerase, NIMA-interacting 1)
Diseases named in the same sentence as PIN1 in open-access papers (continued):
Sharing a sentence is not in itself a finding about the gene and the disease.
breast carcinoma (continued). "Pin1 overexpression in mammary gland induces chromosome instability and leads to breast cancer development and Pin1 ablation effectively prevents tumorigenesis by overexpressing Neu in animal models." (PMID 32500074, 2020). "PIN1 promoter activity is also induced by Neu and Ras signaling via E2F activation in breast cancer." (PMID 32296699, 2020). "PIN1 is overexpressed in several human cancers, including prostate cancer, breast cancer, and oral squamous carcinomas." (PMID 32258027, 2020). "SUMO protease-1 (SENP1) binds to, and deSUMOylates PIN1, and its levels correlate with those of PIN1 in breast cancer." (PMID 32655497, 2020). "Although a positive correlation between PIN1 and Mcl-1 has only been reported in human breast cancer, deregulated Mcl-1 expression is also commonly found in HCC." (PMID 32010690, 2019). "Together, Pin1 was up-regulated in both TAMR human breast cancer cell lines and relapsed tumor tissues, which positively correlated with ERα expression." (PMID 31867329, 2019). "In the current study, we explored the effects of ATRA in inhibiting Pin1 and treating tamoxifen-resistant breast cancer in vitro and in vivo." (PMID 31867329, 2019). "For example, all trans retinoic acid (ATRA) decreases Pin1 expression levels through promoting the degradation of Pin1 protein, thereby suppressing the proliferation of breast cancer cells." (PMID 30899433, 2019). "In metastatic breast cancer cells, PIN1 overexpression controls histone H3K9 trimethylation (H3K9me3) through downregulation of the methyltransferase SUV39H1, fostering tumor growth." (PMID 30873382, 2019). "We have shown that ATRA-induced Pin1 degradation reduces the protein expression of ERα in tamoxifen-resistant breast cancer cells." (PMID 31867329, 2019). "PIN1 over-expression in breast cancer cells has been found to increase expression of mesenchymal cell markers such as N-cadherin, SNAIL and vimentin, and decrease expression of epithelial cell marker E-cadherin." (PMID 32010690, 2019). "Together, these data demonstrate that overexpressing Pin1 in breast cancer cells protects the ERα protein from degradation." (PMID 31867329, 2019). "We found that Pin1 was up-regulated in tamoxifen-resistant human breast cancer cell lines and tumor tissues from relapsed patients." (PMID 31867329, 2019). "PIN1 is overexpressed in breast cancer and mediates its function via RAS signaling, increasing the transcription of c-Jun towards Cyclin D1." (PMID 31083670, 2019). "Our study demonstrated that Pin1 was up-regulated in tamoxifen-resistant breast cancer cells and relapsed breast cancer tissues." (PMID 31867329, 2019). "In order to investigate the effect of Pin1 on expression of YAP/TAZ proteins, we first knocked out Pin1 in MDA-MB-231 breast cancer cells using CRISPR-Cas9, followed by immunoblotting to confirm gene knockout." (PMID 31015482, 2019). "In particular, increased activity is often observed in the majority of human breast cancers, and PIN1 is considered to be an essential factor for breast tumorigenesis, as well as cancer stem cells." (PMID 30789902, 2019). "In summary, our data have shown for the first time that targeting Pin1 by ATRA effectively inhibits the growth of tamoxifen resistant breast cancer." (PMID 31867329, 2019). "Previous study showed that Pin1 inhibited phosphorylation-dependent ubiquitination and degradation of ERα in breast cancer cells." (PMID 31867329, 2019). "Peptidyl-prolyl isomerase Pin1 is prominently overexpressed in breast cancer and involves in tamoxifen-resistance." (PMID 31867329, 2019). "This cross-talk appears to be relevant for morphogenetic processes such as expansion of the mammary gland during pregnancy, while in breast cancers with high levels of PIN1, it confers resistance to selective estrogen receptor modulators, such as tamoxifen." (PMID 30873382, 2019).
breast carcinoma (continued). "Here, we explore the mechanism and effect of targeting Pin1 using its chemical inhibitor all-trans retinoic acid (ATRA) in the treatment of tamoxifen-resistant breast cancer." (PMID 31867329, 2019). "Fourth, PIN1 has been shown to boost the CSC population in breast cancers and it represents a functional node for the cooperation between oncogenic circuitries, reason why tumors, but not normal tissues, are addicted to PIN1." (PMID 30873382, 2019). "In fact, in response to EGF signaling in breast cancer cells, PIN1 spurs SREBP1-dependent induction of the fatty acid synthase FAS, the rate-limiting enzyme of the fatty acid biosynthesis pathway." (PMID 30873382, 2019). "ATO-induced PIN1 degradation results in the suppression of multiple PIN1-mediated oncogenic pathways and inhibition of breast cancer cell proliferation in vitro and in vivo." (PMID 32010690, 2019). "Suppression of Pin1 significantly inhibits the proliferation of breast cancer cells and restores the expression of PML and SMRT80." (PMID 30158600, 2018). "ATRA-induced Pin1 ablation also exerts antitumor activity against breast cancer by blocking multiple oncogenic pathways." (PMID 30093655, 2018). "Pin1 enhances the IL-22-induced proliferation and survival of breast cancer cells by activating mitogen-activated extracellular signal-regulated kinases, c-Jun, and STAT3180." (PMID 30158600, 2018). "PIN1 knockdown significantly reduced LYN Y397 phosphorylation in a human BRCA2 mutant breast cancer cell line and in primary mouse Brca2 null tumor cells." (PMID 30590041, 2018). "Mechanically, Pin1 promotes breast cancer stem cell (BCSC)-proliferation and tumorigenesis in vitro and in vivo by increasing Rab2A transcription and thereby Erk activation, Zeb1 upregulation, and β-catenin nuclear translocation." (PMID 29848341, 2018). "When the same residue was phosphorylated in mouse embryonic fibroblasts and breast cancer cells, Pin1 was detected out of the nucleus." (PMID 30096758, 2018). "Together, these observations suggest that PIN1-mediated mechanisms are important for cancer cell invasion in glioblastoma, a possibility also consistent with a role of PIN1 in supporting cell invasion in breast cancer." (PMID 30314361, 2018). "The relationship between miRNAs and PIN1 expression was first demonstrated in breast cancer with miR-200b shown to be down-regulated and inversely correlated with PIN1 expression in breast tumor tissues." (PMID 30534074, 2018). "Both E2F (E2 factor), a protein involved in the cell cycle regulation, and N1ICD (Notch Intracellular Domain), a protein that regulates Pin1 generating a positive loop in breast cancer cells, are able to activate transcription of Pin1 upon binding." (PMID 30096758, 2018). "The garlic extract diallyl trisulfide-treated breast cancer cells exhibit a reduced expression of Pin1 along with reduced ERα activity and cell proliferation." (PMID 30158600, 2018). "In PLC/PRF/5 HCC cells, ATRA began to induce Pin1 degradation at 5 μM, a little higher in comparison with ~1 μM in the breast cancer and APL cells." (PMID 28262728, 2017). "ATRA binds to active Pin1 selectively in cancer cells, leading to its degradation and exerting potent anti-tumor activity against acute promyelocytic leukemia and breast cancer." (PMID 28404959, 2017). "Previous studies have shown that PIN1 inhibition can suppress the Neu- and Ras-induced transformed phenotypes, in addition to inducing mitotic arrest and apoptosis in breast cancer cells." (PMID 27258148, 2016). "Our findings concur with those of studies on human breast cancer in which PIN1 overexpression resulted in increased JNK activity." (PMID 27258148, 2016). "Further, PIN1 participates in EMT processes within drug-resistant breast cancer, and drives invasiveness and tumorigenicity of A375 melanoma cells in murine models." (PMID 27852308, 2016).
breast carcinoma (continued). "Tpl2 directly interacts with Peptidyl-prolyl cis-trans isomerase NIMA-interacting 1 (Pin1) and induces the phosphorylation of Pin1 on Ser16, which results in cyclin D1 up-regulation and breast cancer development." (PMID 25723737, 2015). "In support of a mechanistic role of EMT in tamoxifen resistance of breast cancer cells, over-expression of Pin-1, AKT, Nicastrin and Notch4, FoxM1, brachyury as well as modulation of several microRNAs has been reported." (PMID 26206152, 2015). "Taken together, these results indicate that the overexpression of Pin1 is concomitant with Rb hyperphosphorylation in human breast cancer." (PMID 25675300, 2015). "Here we found that the overexpression of Pin1 correlates with increased Rb phosphorylation in breast cancer." (PMID 25675300, 2015). "Pin1 depletion by siRNA in MDA-MB-231 breast cancer cells treated with gamma-secretase inhibitor to blunt Notch cleavage at the membrane, caused a strong decay of cytoplasmic N1-ICD." (PMID 24357640, 2014). "It has been reported that PIN1 is aberrantly overexpressed in numerous types of cancer, including prostate and lung cancer, esophageal squamous cell carcinoma, and breast cancer." (PMID 25120724, 2014). "Having dissected the biochemistry of the Pin1/Fbxw7α antagonism in the Notch pathway, we next investigated the impact of this interplay on the stem cell functions of Notch signaling in breast cancer cells." (PMID 24357640, 2014). "Pin1 also modulates the protein stability of estrogen receptor-alpha (ERα), an important biomarker for breast cancer, by blocking ERα protein ubiquitination and transcription of the ERα mRNA." (PMID 24416409, 2014). "Expression of Pin1 inversely correlates with the expression of RUNX3 in human breast cancer samples." (PMID 23708493, 2013). "Overall, our results suggest a new pathway that involves PI3K/AKT, CDK2 and Pin1 and open up new opportunities for treating ERalpha-positive breast cancer patients who are resistant to hormonal therapy." (PMID 23390529, 2013). "Our data strongly suggest that inhibition of Cdk2 and/or Pin1 in ERα-positive and ErbB2-positive breast cancer cells will enhance the anti-tumor activity of tamoxifen." (PMID 19383165, 2009). "Pin1 overexpression is prevalent in many different cancers including breast cancer and there is strong correlation between its overexpression and breast cancer in patients." (PMID 19383165, 2009). "Pin1 inhibition alone and in conjunction with mTOR inhibition suppresses the growth of Her2+ breast cancer cells." (PMID 19077306, 2008). "The goal of this study was to examine the expression of prolyl isomerase Pin1 in human Her2+ breast cancer, and to study if Pin1 affects the expression of Her2/Neu itself." (PMID 19077306, 2008). "Sixty-four samples (28.7%) stained positive for Her2 (IHC 3+), and 54% (122/223) of all breast cancers stained positive for Pin1." (PMID 19077306, 2008). "It is important to note, however, that in the mouse model, we showed that Pin1 ablation prevented breast cancer, while in the current experiments we attempted to inhibit the growth of actual cancer cells." (PMID 19077306, 2008). "Here, we report that Pin1 overexpression is found in 62% of Her2-positive breast cancer, and that Pin1 inhibition suppresses the growth of Her2-positive breast cancer cells." (PMID 19077306, 2008). "We have previously shown that Pin1 null mice were largely protected from breast cancers induced by the c-neu transgene." (PMID 19077306, 2008). "To inhibit Pin1, we optimized Pin1-specific siRNA transfection with a 20-mer directed against the 5' portion of Pin1 and achieved near-complete ablation of Pin1 in all breast cancer cell lines examined within 72 hours of transfection." (PMID 19077306, 2008). "To examine the effect of Pin1 inhibition on the growth pattern of breast cancer with Her2-amplification, we used siRNA inhibition of Pin1 in the Her2-positive cell lines AU565, BT474 and SKBr3." (PMID 19077306, 2008).
breast carcinoma (continued). "Immunohistochemistry for Her2 and Pin1 were performed on two hundred twenty-three human breast cancers, with 59% of the specimen from primary cancers and 41% from metastatic sites." (PMID 19077306, 2008). "These in vitro and in vivo data point toward Pin1 as a potential therapeutic target in adenocarcinomas, and specifically Her2+ breast cancer." (PMID 19077306, 2008). "As a first step, we set out to examine the frequency of Pin1 overexpression in Her2+ human breast cancer." (PMID 19077306, 2008). "Pin1 inhibition was achieved using siRNA in Her2+ breast cancer cell lines, and its effects were studied using cell viability assays, immunoblotting and immunofluorescence." (PMID 19077306, 2008). "A total of 223 breast cancer specimens, mostly from primary tumors, were analyzed by immunohistochemistry for Her2 and Pin1 expression." (PMID 19077306, 2008). "SENP1-mediated deSUMOylation enhances PIN1 activity in breast cancer." (PMID 41438340, 2026). "According to certain research, PIN1 regulates the translation of mRNA, and the PIN1/METTL3 axis may serve as an alternative therapeutic target for breast cancer." (PMID 40919129, 2025). "Additionally, in tamoxifen-resistant breast cancer, elevated levels of Pin1 enhance its interaction with p-MEK1/2, resulting in increased E2F-4- and Egr-1-driven LC-3 expression." (PMID 38711994, 2024). "Notably, the therapeutic effect was similarlyconfirmed in a mouse breast cancer model overexpressing Pin1." (PMID 39051165, 2024). "Indeed, induced degradation of Pin1 by all-trans-retinoic acid (ATRA) effectively inhibits breast cancers and leukemia." (PMID 38167292, 2024). "Importantly, juglone, which is known to induce the apoptotic process through PIN1 inhibition, has been shown to have anti-tumor effects in pancreatic, prostate, melanoma, colorectal, glioblastoma, and breast cancers." (PMID 39202474, 2024). "Structurally, Pin1 comprises N- and C-terminal PPIase domains that play roles in mediating cellular processes and regulating multiple human cancers, including prostate cancer, breast cancer, oral squamous carcinoma, and nasopharyngeal carcinoma (NPC)." (PMID 39624096, 2024). "Similarly, miR-200b has been found to have a significant influence on breast cancer metastasis by directly targeting the 3′-UTR of Pin1 mRNA, thereby regulating Pin1 expression at the translational level." (PMID 39624096, 2024). "Similarly, tamoxifen resistance is conferred on and enhanced in breast cancer cells by Pin1-mediated SGK1 degradation." (PMID 38727267, 2024). "Moreover, as key elements in the development of new anticancer drugs, benzimidazole derivatives can inhibit Pin1, thereby contributing to targeted treatment for prostate and breast cancer." (PMID 39624096, 2024). "Since ATRA-mediated inhibition of PIN1 inhibited breast cancer, leukemia, and liver cancer." (PMID 36760500, 2023). "Pin1 mediates tamoxifen resistance in the MCF-7 breast cancer cell line by increasing the mRNA and protein expression of LC-3, a marker for autophagy, which is believed to be utilized by cancer cells as a coping scheme for survival at the point of drug selection." (PMID 37508437, 2023). "We also found that pVHL was more stable in ER+ (MCF-7) and HER2+ (SK-BR-3) breast cancer cell lines when PIN1 was knockdown by specific shRNA, which could be due to the decreased ubiquitination of pVHL." (PMID 36813923, 2023). "Therefore, it is important to increase the sample size to further investigate the roles of TPL2 and Pin1 in the occurrence and development of breast cancer and their effects on treatment and prognosis." (PMID 37833434, 2023). "Furthermore, KPT-6566 demonstrates efficient cell permeability and inhibitory effects on Pin1 function, both in vitro and in vivo, as evidenced by its ability to suppress lung metastasis in a breast cancer in mouse model." (PMID 37508437, 2023). "PIN1 also enhances STAT3-mediated EMT induced by Oncostatin M in breast cancer cells." (PMID 36813923, 2023).
breast carcinoma (continued). "This suggests that PIN1 regulates METTL3 through ubiquitination in breast cancer." (PMID 37391814, 2023). "In addition, METTL3 expression has been shown to significantly increase with tumor progression and positively correlate with peptidyl-prolyl cis-trans isomerase NIMA-interacting 1 (PIN1) expression in breast cancer tissues." (PMID 37391814, 2023). "Importantly, CNTLN was reported as a PTB-related gene, and PIN1 involves inhibition of breast cancer." (PMID 36788602, 2023). "The sensitivity of breast cancer cells to KPT-6566 also correlates with Pin1 expression." (PMID 36923534, 2023). "Interestingly, compared with normal tissues and other breast cancer subtypes, Pin1, and TAZ are more highly expressed in TNBC." (PMID 35450041, 2022). "Although the function of PIN1 has been studied extensively, it is unclear whether PIN1 participates in the IL-36γ signaling pathway during breast cancer development." (PMID 35954317, 2022). "In continuation of our previous work targeting breast cancer via Pin1 inhibition, herein we design new benzimidazoles by altering the carboxylic group of compound II with different substitutions at the 2-position to give new products with expected improved activity." (PMID 36014485, 2022). "Quercetin was examined in tamoxifen (TAM)-resistant MCF-7 cells and its ability to inhibit Pin1 suggested that it could be useful to treat TAM-resistant breast cancer." (PMID 36355532, 2022). "In a study on breast cancer, the researchers found that PIN1 could induce the expression of LC-3 and there was a positive correlation between the levels of LC-3 and PIN1 in human breast cancer." (PMID 36340199, 2022). "Additionally, they found that all-trans retinoic acid inhibits leukemia, breast cancer, and liver cancer by targeting isomerase Pin1." (PMID 36393861, 2022). "Interestingly, in our previous report, the PIN1 inhibitor juglone suppressed the IL-22-induced tumorigenic potential of human breast cancer MCF7 cells via MAPK signaling." (PMID 35954317, 2022). "In addition, juglone, a PIN1 inhibitor, suppressed tumor growth of breast cancer cells by inhibiting the activity of PIN1 in syngeneic models in vivo." (PMID 35954317, 2022). "Furthermore, PIN1 enhances IL-34-induced breast cancer development via activation of the MEK/ERK and JNK/c-Jun signaling pathways." (PMID 35954317, 2022). "Interestingly, blocking PIN1 activity using juglone suppressed the IL-36γ-induced increase in the anchorage-independent growth of 4T1 metastatic mouse breast cancer cells." (PMID 35954317, 2022). "A strong correlation between Pin1 overexpression and high levels of activated Notch1 has been observed in breast cancer patients, and some studies have suggested that Notch1 may directly induce transcription of Pin1." (PMID 36304997, 2022). "This evidence supports our hypothesis that PIN1 regulates IL-36γ-induced epithelial cell transformation and tumorigenesis in breast cancer." (PMID 35954317, 2022). "Furthermore, MAP3K-related serine/threonine kinase COT has been reported to phosphorylate Pin1 at Ser16, which consequently stabilizes cyclin D1 protein and promotes tumorigenesis in breast cancer cells." (PMID 33807199, 2021). "Pin1 can destabilize PML to promote the proliferation of breast cancer cells." (PMID 33807199, 2021). "In breast cancer, Pin1 could promote cell proliferation through increased protein stability, DNA binding affinity and transcriptional activity of ERα." (PMID 33807199, 2021). "Furthermore, Pin1 stabilizes Mcl-1, which promotes chemoresistance, thereby making it positively correlated with poor survival in human breast cancer." (PMID 33807199, 2021). "Overall, our study highlights the previously unknown role of IL-34/CSF1R signaling in breast cancer and demonstrates the regulatory role of PIN1 in IL-34-induced tumorigenesis." (PMID 33800170, 2021).